TBCCD1 (TBCC domain containing 1)
Description:
Plays a role in the regulation of centrosome and Golgi apparatus positioning, with consequences on cell shape and cell migration.
Synonyms: FLJ10560
Tractability: PROTAC: ubiquitination databases record sites on it.
Gene: Protein-coding gene on chromosome 3 (186,546,067 to 186,570,543, reverse strand). Ensembl gene ENSG00000113838.
Subcellular location: Cytoplasm, cytoskeleton, microtubule organizing center, centrosome; Cytoplasm, cytoskeleton, spindle pole
Gene Ontology:
Molecular function: protein binding
Biological process: maintenance of centrosome location; maintenance of Golgi location; regulation of cell migration; regulation of cell shape
Cellular component: spindle pole centrosome; centrosome; spindle pole
Genetic constraint (gnomAD): Loss-of-function variants: 26 observed, 54.17 expected, observed/expected ratio (o/e) 0.48, 90% interval 0.35 to 0.67. The upper end of that interval is the gene's LOEUF score, 0.67, which puts it in group 2 of 6, group 1 being the genes least tolerant of losing a copy. Missense variants: 558 observed, 701.72 expected, observed/expected ratio (o/e) 0.8, 90% interval 0.74 to 0.85. Synonymous variants: 245 observed, 254.93 expected, observed/expected ratio (o/e) 0.96, 90% interval 0.87 to 1.07.
Homologues: Orthologues: chimpanzee TBCCD1 (99% identical), macaque TBCCD1 (98% identical), dog TBCCD1 (93% identical), pig TBCCD1 (91% identical), guinea pig TBCCD1 (89% identical), rabbit TBCCD1 (84% identical), mouse Tbccd1 (82% identical), rat Tbccd1 (82% identical), tropical clawed frog tbccd1 (58% identical), zebrafish tbccd1 (56% identical), Caenorhabditis elegans C54G6.2 (18% identical).
Diseases named in the same sentence as TBCCD1 in open-access papers:
TBCCD1 is named in the same sentence as 1 disease in open-access papers, as found by Europe PMC text mining. Sharing a sentence is not in itself a finding about the gene and the disease. The quoted sentences say what the papers report.
cancer (2 papers, 2019 to 2020). A tumor composed of atypical neoplastic, often pleomorphic cells that invade other tissues. "Taking all these data into account, we identified the following candidates as potential causes of CA in human cancer: gain of function of CEP19, CEP72, CTNNB1, PTK2, NDRG1, SPATC1, TBCCD1; and loss of function of CEP76, MCPH1, NEURL4, NPM1." (PMID 32681070, 2020). "TBCCD1, a key regulator of centrosome positioning and consequently of internal cell organization, is a new centrosomal protein, and it has not been mentioned in any cancer." (PMID 31472672, 2019).